TXN (thioredoxin)
Description:
Participates in various redox reactions through the reversible oxidation of its active center dithiol to a disulfide and catalyzes dithiol-disulfide exchange reactions. Plays a role in the reversible S-nitrosylation of cysteine residues in target proteins, and thereby contributes to the response to intracellular nitric oxide. Nitrosylates the active site Cys of CASP3 in response to nitric oxide (NO), and thereby inhibits caspase-3 activity. Induces the FOS/JUN AP-1 DNA-binding activity in ionizing radiation (IR) cells through its oxidation/reduction status and stimulates AP-1 transcriptional activity. ADF augments the expression of the interleukin-2 receptor TAC (IL2R/P55).
Synonyms: Trx; TRDX; TRX1; Trx80; TXN1
Tractability: Small molecule: a drug acting on it is in phase 2 or 3 trials; a structure with a bound ligand is known; a high-quality ligand is known; it belongs to a druggable protein family. Antibody: UniProt places it where antibodies can reach, with high confidence; its Gene Ontology location is reachable by antibodies, with high confidence. PROTAC: UniProt records ubiquitination sites on it; ubiquitination databases record sites on it; its protein half-life has been measured; a small molecule that binds it is known.
Target class: Enzyme; Oxidoreductase
Gene: Protein-coding gene on chromosome 9 (110,243,810 to 110,256,604, reverse strand). Ensembl gene ENSG00000136810.
Subcellular location: Nucleus; Cytoplasm; Secreted
Subcellular location (Human Protein Atlas): Cytosol; Nucleoplasm
Pathways (Reactome):
Cellular responses to stimuli: Detoxification of Reactive Oxygen Species; NFE2L2 regulating anti-oxidant/detoxification enzymes; Oxidative Stress Induced Senescence
Gene expression (Transcription): Regulation of FOXO transcriptional activity by acetylation
Disease: Purinergic signaling in leishmaniasis infection
Immune System: The NLRP3 inflammasome
Metabolism: Interconversion of nucleotide di- and triphosphates
Metabolism of proteins: Protein repair
Gene Ontology:
Molecular function: protein binding; protein homodimerization activity; protein-disulfide reductase [NAD(P)H] activity; protein-disulfide reductase activity; RNA binding; thioredoxin-disulfide reductase (NADPH) activity
Biological process: cell redox homeostasis; cellular detoxification of hydrogen peroxide; positive regulation of DNA binding; positive regulation of phosphatidylinositol 3-kinase/protein kinase B signal transduction; response to nitric oxide; response to radiation
Cellular component: cytoplasm; cytosol; extracellular exosome; extracellular region; nucleoplasm; nucleus
Genetic constraint (gnomAD): Loss-of-function variants: 4 observed, 6.09 expected, observed/expected ratio (o/e) 0.66, 90% interval 0.32 to 1.47. That is too few expected variants to judge how well the gene tolerates losing a copy. Missense variants: 37 observed, 66.16 expected, observed/expected ratio (o/e) 0.56, 90% interval 0.43 to 0.74. Synonymous variants: 23 observed, 22.43 expected, observed/expected ratio (o/e) 1.03, 90% interval 0.74 to 1.45.
Homologues: Orthologues: chimpanzee TXN (100% identical), macaque TXN (96% identical), dog TXN (95% identical), guinea pig Txn (92% identical), rat Txn1 (89% identical), mouse Txn1 (88% identical), zebrafish txnb (64% identical), zebrafish txna (60% identical). Paralogues in human: TXNDC2 (60% identical), TXNDC8 (50% identical), TXNL1 (46% identical), TXN2 (34% identical).
Diseases named in the same sentence as TXN in open-access papers:
TXN is named in the same sentence as 228 diseases in open-access papers, as found by Europe PMC text mining. Sharing a sentence is not in itself a finding about the gene and the disease. The quoted sentences say what the papers report.
breast carcinoma (35 papers, 2007 to 2025). "TXN, on the other hand, has been associated in breast cancer with resistance to both docetaxel and trastuzumab." (PMID 34948097, 2021). "TXN is associated with poor prognosis in breast cancer patients." (PMID 36614036, 2022). "The findings above prompted us to investigate whether other members of the thioredoxin pathway and downstream factors are also associated with prognosis of breast cancer." (PMID 20584310, 2010). "In addition, high thioredoxin expression in prechemotherapy tumor samples has been reported to be associated with resistance to docetaxel in primary breast cancer." (PMID 20584310, 2010). "Ferrotocide, a diterpenoid natural product, is a thioredoxin inhibitor which inducs ferroptosis of breast cancer by inactivating thioredoxin (a cell antioxidant enzyme)." (PMID 38783959, 2024). "Targeting cysteine transportation by SSA, glutathione synthases by BSO, and thioredoxin production by Auranofin showed a significant anti-tumor response in breast cancer." (PMID 34924003, 2021). "In another study, high levels of reduced TXN caused the failure of trastuzumab to activate phosphatase and tensin homolog (PTEN), and TXN inhibition was required for sensitization of breast cancer cells resistant to anti-HER2 therapy." (PMID 34948097, 2021). "This study provides important evidence of the roles of the thioredoxin system as an exploitable radiobiological target in breast cancer cells and highlights the potential therapeutic value of indolequinones as radiosensitisers." (PMID 33768386, 2021). "The thioredoxin (Trx) system is currently being studied as a novel target in overcoming drug resistance in other cancers, such as multiple myeloma and breast cancer." (PMID 32138149, 2020). "Consistently, we show here that silencing of TXN strongly decreases the survival and migration of breast cancer cells under oxidative stress." (PMID 29755668, 2018). "Accordingly, high expression of TXN and TXNRD1 has been previously associated to high grade breast cancers." (PMID 29755668, 2018). "For instance, thioredoxin, a redox protein with growth factor activity (F2++) increases cell proliferation of breast cancer cells." (PMID 24997799, 2014). "We have found six polymorphisms in OGG1, GPX6, SOD3, TXN and XDH genes significantly associated with predisposition to breast cancer." (PMID 25416100, 2014). "In order to understand the role of TXNRD1 and TXNIP for the natural history of breast cancer it seemed relevant to focus on untreated patients, because the thioredoxin system has been reported to influence sensitivity of tumor cells to chemotherapy." (PMID 20584310, 2010). "Targeting thioredoxin reductase and thioredoxin has been suggested recently as a basis for cancer therapy, including breast cancer." (PMID 20584310, 2010). "High expression of TXN and TXNRD1 with low expression of TXNIP was associated with dysfunctional T cell phenotype and shorter survival of the breast carcinoma cohort and colorectal carcinoma cohort, in accordance with the abnormal expression status of the Trx system in BRCA and COAD." (PMID 39744566, 2025). "In addition, it was showed that TXN was over-expressed in human breast carcinoma tissues and the expression level was correlated with tumor grade." (PMID 28107202, 2017).
breast carcinoma (continued). "Also, hyperglycemia regulates thioredoxin-ROS activity through induction of TXNIP in breast cancer derived cells." (PMID 25605021, 2015). "The thioredoxin system is highly conserved throughout evolution and we observed that multiple members of this system are highly overexpressed in multiple cancers (group 6) and confer dismal prognosis in lung and breast cancers." (PMID 24342878, 2013). "Besides, breast cancer 1 (BRCA1)-deficient cells were sensitized to the BET inhibitor, which reversed the MYC/TXNIP axis by inhibiting the activity of thioredoxin and elevating cellular oxidative stress, causing DNA damage that led to the death of BRCA1-deficient breast cancer cells." (PMID 35547739, 2022). "The following genes were reported to be lower expressed in breast cancer samples of cases compared to controls in two different studies but were reported to be higher expressed in another study: PABPC1, ARPC1A, TXN, TOB1." (PMID 36627894, 2022). "Since either PHA treatment or Baf A1/PHA cotreatments induced ROS, the effects of autophagy in antioxidant gene expressions such as SOD1, NFE2L2, TXN, and GSR in breast cancer cells were assessed by real-time PCR." (PMID 35883843, 2022). "Using siRNA to silence Cul3 in breast cancer cells, microarray analysis revealed that the expressions of oxidative stress downstream genes (AKR1C1, UGDH, TXN, GCL, and NQO1) were overexpressed at least 2-fold." (PMID 35242279, 2022). "Peroxiredoxin-1 (Prdx1), a member of the thioredoxin (Txn) system, is overexpressed and correlates with poor prognosis in pancreatic cancer patients and can suppress Kras signaling through redox-mediated inhibition of ERK and AKT in lung and breast cancer." (PMID 29190947, 2017). "Additional associations with MFI found for thioredoxin and downstream factors of the thioredoxin pathway, including PRDX2, RRM2, HIF1A and VEGF, confirm the importance of the thioredoxin system in breast cancer regardless of its ROS-related or unrelated roles." (PMID 20584310, 2010). "Indeed, we also observed the low expression of TXNDR1 compared with TXN in this study, which may be relevant to the HER2-negative breast carcinomas." (PMID 33462336, 2021).
diabetes (30 papers, 2010 to 2026). "Fenofibrate rescues diabetes-associated ischemia-mediated angiogenesis impairment by mercaptopurine independent regulation of thioredoxin interactions." (PMID 38168477, 2024). "TXNIP is an endogenous thioredoxin inhibitor that was later found to be elevated in rodent models of diabetes and has therefore been associated with the β-cell response to stress." (PMID 34557160, 2021). "Additionally, we analyzed expression of Txnip—a thioredoxin interaction protein ascribed a pathogenic role in diabetes and related complications, whose expression is strongly up-regulated by glucose in normal physiology." (PMID 35600617, 2022). "TXN, as a key regulator of oxidative stress, is increasingly recognized for its role in diabetes and its complications." (PMID 41503916, 2026). "These two studies were also conducted on a Slovenian population and from these results we can infer that genetic variation in the thioredoxin antioxidant system influences the development of complications related to diabetes in a Slovenian population." (PMID 40076459, 2025). "Previous studies have indicated that Txnip, by suppressing the antioxidant activity of thioredoxin, plays a significant role in the pathogenesis of diabetes." (PMID 40508179, 2025). "The overexpression of Thioredoxin (Trx) has been found to delay cochlear hair cell degeneration induced by diabetes by regulating various cellular processes." (PMID 38985787, 2024). "Polymorphisms of genes involved in diabetes pathogenesis, including IL8RA, TXN, NR3C2, COX5A, and GCLC, significantly modulated the association between urinary As levels and the odds of diabetes in a general Spanish population." (PMID 37624175, 2023). "Thioredoxin overexpression delays the onset of diabetes and protects against β-cell cytotoxicity induced by streptozotocin (STZ), a β-cell toxin." (PMID 34557160, 2021). "Another study indicated that STZ produced its deleterious metabolic effect in diabetes through the downregulation of the thioredoxin activity and enhanced the levels of Trxip mRNA in diabetic rat brains." (PMID 31998774, 2020). "VMH thioredoxin overexpression completely normalized GI neuronal glucose sensing, glycemia recovery, and glucagon secretion in rats with type 1 diabetes mellitus." (PMID 29593556, 2018). "Second, the effects of N-acetylcysteine were more pronounced during RH whereas VMH thioredoxin overexpression was more effective in diabetes." (PMID 29593556, 2018). "The antioxidant enzymes usually studied in diabetes include catalase, superoxide dismutase, glutathione system, and thioredoxin system." (PMID 26317017, 2013). "Clearly, the thioredoxin (TRX)-system is involved in the pathophysiology of diabetes as well." (PMID 39068204, 2024). "Methylglyoxal is a well-described GDP in PD fluids and diabetes mellitus, and may impair the TXN/TXNRD1 and glutathione reductase (GSR) system in several cell types including aortic endothelial cells." (PMID 35887356, 2022). "TXNIP expression is highly triggered by glucose and is increased in the beta-cells (β-cells) of patients with diabetes, inhibiting TXN function and inducing increased levels of freely diffusible molecular hydrogen peroxide; it contributes to oxidative stress and eventually β-cell death." (PMID 34500775, 2021). "It will also be important to determine whether the effects of thioredoxin persist in type 2 diabetes mellitus or in other models of type 1 diabetes." (PMID 29593556, 2018). "Several components of the thioredoxin system are closely linked to LRRK2, including PRDX3, TXNIP, and TXNRD1, which have been identified in recent years as risk factors for obesity and diabetes in human subjects, and as nutrient sensing mechanisms and controlling factors of adipogenesis in mice." (PMID 23799078, 2013).
diabetes (continued). "Although TXNIP was initially identified as a protein interacting with thioredoxin and modulating cellular responses to oxidative stresses, it has the ability to inhibit glucose uptake and is being recognized as an important regulator of dysregulated metabolism in diabetes." (PMID 20844768, 2010). "Deficiencies in antioxidant defenses against ROS described in diabetes included antioxidant enzyme such as SOD1, PRDX1, Hmox1 and antioxidants, thioredoxin 1 (Txn1)." (PMID 37337262, 2023). "Thioredoxin (TXN) and thioredoxin-interacting protein (TXNIP) are reduction-oxidation signaling complex that play crucial roles in oxidative stress- and inflammation-mediated diseases, such as diabetes, autoimmune disease, cancer, and apoptosis." (PMID 40248092, 2025). "Thioredoxin can bind to signalling molecules such as ASK-1 and TXNIP that potentially influence cell growth and survival in diverse human diseases such as cancer, diabetes, and heart disease 19,20." (PMID 25858687, 2015). "In contrast, thioredoxin mRNA levels did not change in either tissue at these timepoints of diabetes." (PMID 25329046, 2014). "First, while virtually all animals injected with the control vector developed diabetes after one injection of the β-cell toxin streptozotocin, one quarter of the VMH thioredoxin overexpressing animals did not." (PMID 29593556, 2018).
lung carcinoma (18 papers, 2013 to 2026). "Assessments of the effects of TXN expression on survival of lung cancer patients showed that TXN was associated with OS (P = 0.024, HR 1.26, 95% CI: 1.03-1.56), but its predictive power was weak (AUC 0.568, 95% CI: 0.534-0.605)." (PMID 36776308, 2023). "The association between TXN expression and lung cancer was verified by immunohistochemical analysis of the Human Protein Atlas database, as well as by western blotting and qPCR." (PMID 36776308, 2023). "Prognostic analysis in the present study showed that high TXN expression was associated with poor prognosis in patients with lung cancer." (PMID 36776308, 2023). "Multivariable analysis showed that T stage (T3/T4), N stage (N2/N3), pathological stage (III/IV), curative outcomes (PD), and high expression of TXN were key risk factors for lung cancer survival." (PMID 36776308, 2023). "For example, increased expression of the antioxidant thioredoxin-1 (TXN) is associated with lower ROS and decreased cisplatin-resistance in a lung cancer cell line." (PMID 34645978, 2021). "TXN expression was associated with both analyses, suggesting that TXN may be an optimal target in lung cancer treatment." (PMID 36776308, 2023). "Intriguingly, we discovered that lung cancer patients with high levels of TXN and TXNRD1 expression had shorter survival duration and dysfunctional T cell phenotype." (PMID 39744566, 2025). "The biological functions and clinical significance of TXN in lung cancer were further assessed by in-depth analyses." (PMID 36776308, 2023). "In the present study, several datasets from the TCGA and GEO databases were selected, with screening of differentially expressed and hub genes identifying TXN as a target gene in lung cancer." (PMID 36776308, 2023). "The immunohistochemical levels of expression of TXN in normal lung and lung cancer tissues were obtained from the HPA database." (PMID 36776308, 2023). "In conclusion, the present study, which utilized bioinformatics methods to identify lung cancer oxidative stress related genes, found that TXN was related to the prognosis of lung cancer and had certain predictive value." (PMID 36776308, 2023). "These analyses showed that TXN was differentially expressed in lung cancer and normal lung tissue and that TXN had prognostic characteristics in lung cancer." (PMID 36776308, 2023). "The relationships between TXN expression and pathological characteristics of patients with lung cancer were further evaluated by KM survival analysis." (PMID 36776308, 2023). "TXN was also found to be more highly expressed in lung cancer than in normal lung epithelial cell lines." (PMID 36776308, 2023). "Evaluation of cell lines showed that TXN mRNA and protein expression levels were higher in the lung cancer cell lines than in the normal lung epithelial cell line." (PMID 36776308, 2023). "Cox regression analysis, functional enrichment, and analyses of survival and prognosis showed that TXN was predictive of the diagnosis and prognosis of lung cancer." (PMID 36776308, 2023). "The activity of thioredoxin and glutathione S‐transferase in lung cancer cells lines was also inhibited by covalent binding of SFN to their cysteine residues." (PMID 32926463, 2020). "Downregulation of TXN in lung cancer results in an increased reactive oxygen species and alters tumor metabolism, resulting in cisplatin resistance." (PMID 29868478, 2018). "The data suggest a greater dependence of liver on either the thioredoxin or glutathione system to drive the malignancy, while lung cancer appeared to depend primarily on the thioredoxin system." (PMID 26569310, 2015).